PCDH19 (protocadherin 19)
Description:
Calcium-dependent cell-adhesion protein.
Synonyms: KIAA1313; EIEE9; DEE9; EFMR
Tractability: Antibody: UniProt places it where antibodies can reach, with medium confidence; UniProt predicts a signal peptide or a membrane-spanning region; its Gene Ontology location is reachable by antibodies, with medium confidence. PROTAC: its protein half-life has been measured.
Gene: Protein-coding gene on chromosome X (100,291,644 to 100,410,296, reverse strand). Ensembl gene ENSG00000165194.
Subcellular location: Cell membrane
Subcellular location (Human Protein Atlas): Cytosol
Pathways (Reactome):
Developmental Biology: Formation of the nephric duct
Gene Ontology:
Molecular function: cell adhesion molecule binding; calcium ion binding
Biological process: cell adhesion; homophilic cell-cell adhesion
Cellular component: plasma membrane; membrane
Gene-disease validity (ClinGen):
ClinGen rates the evidence that PCDH19 causes each of these diseases.
X-linked complex neurodevelopmental disorder (X-linked): Definitive. A complex neurodevelopmental disorder that is transmitted via X-linked inheritance, and is characterized by intellectual disability, autism and epilepsy.
Homologues: Orthologues: chimpanzee PCDH19 (99% identical), macaque PCDH19 (99% identical), pig PCDH19 (98% identical), mouse Pcdh19 (96% identical), rabbit PCDH19 (96% identical), rat Pcdh19 (96% identical), guinea pig PCDH19 (96% identical), tropical clawed frog pcdh19 (79% identical), zebrafish pcdh19 (67% identical). Paralogues in human: PCDH17 (48% identical), PCDH10 (30% identical), PCDH18 (30% identical), PCDH8 (27% identical), PCDHAC2 (27% identical), PCDHGA4 (26% identical), PCDHB15 (26% identical), PCDHB3 (26% identical), PCDHB10 (25% identical), PCDHB7 (25% identical), PCDHGA11 (25% identical), PCDHGA9 (25% identical), and 49 more.
Diseases named in the same sentence as PCDH19 in open-access papers:
PCDH19 is named in the same sentence as 88 diseases in open-access papers, as found by Europe PMC text mining. Sharing a sentence is not in itself a finding about the gene and the disease. The quoted sentences say what the papers report.
epilepsy (134 papers, 2009 to 2026). A brain disorder characterized by episodes of abnormally increased neuronal discharge resulting in transient episodes of sensory or motor neurological dysfunction, or psychic dysfunction. "PCDH19 clustering epilepsy is a rare monogenic epilepsy syndrome caused by a loss-of-function mutation of the protocadherin-19 (PCDH19) gene, which encodes a calcium-dependent adhesion molecule involved in cell-cell adhesion and synaptic communication." (PMID 41585885, 2025). "For example, PCDH19-related epilepsy is caused by heterozygous loss-of-function mutations in the X-linked gene, PCDH19." (PMID 40870033, 2025). "The hallmark feature of PCDH19-associated epilepsy is that seizures occur in clusters, lasting hours to days, often induced by fever, with onset around the first year of life." (PMID 38612920, 2024). "Protocadherin 19 (PCDH19) is an adhesion molecule involved in cell-cell interaction whose mutations cause a drug-resistant form of epilepsy, named PCDH19-Clustering Epilepsy (PCDH19-CE, MIM 300088)." (PMID 39834389, 2024). "The DEE9 or Protocadherin 19 (PCDH19) clustering epilepsy, is an X-linked disorder that displays specific clinical characteristics, as reviewed above." (PMID 39457436, 2024). "In this study, we screened 165 patients with epilepsy and found PCDH19 mutation in 5 female patients with idiopathic Dravet-like epileptic encephalopathy and psychiatric abnormalities." (PMID 38891919, 2024). "Genomic variants in the X-linked PCDH19 gene causePCDH19-clustering epilepsy (PCDH19-CE), one of the most common forms of inheritedepilepsy, which is characterized by variable seizures and incompletely penetrantintellectual disability." (PMID 38629124, 2024). "Developmental and epileptic encephalopathy 9 (DEE9) (MIM #300088), also known as Protocadherin 19 (PCDH19) clustering epilepsy, is an X-linked disorder caused by heterozygous pathogenic variants in the PCDH19 gene." (PMID 39457436, 2024). "The aim of our study was to characterize the detected two novel and three reported mutations in our patient cohort in order to better understand the clinical features and the mutational spectrum of PCDH19-related epilepsy." (PMID 38891919, 2024). "This role of cellular interference in the pathogenesis of PCDH19-associated epilepsy is further supported by a case report describing a male with Klinefelter syndrome (XXY) who is heterozygous for PCDH19 mutation presenting with early onset epileptic seizures." (PMID 36980870, 2023). "A complete PCDH19 ectodomain model was put forward recently, which can assist in the evaluation of epilepsy-related variants and protein interaction sites." (PMID 36970538, 2023). "PCDH19 epilepsy (DEE9) is an X-linked syndrome associated with cognitive and behavioral disturbances." (PMID 35741068, 2022). "Disease-causing variants in PCDH19 lead to early-onset DEE with clustering epilepsy (CE) as well as altered steroidogenesis and nuclear-hormone-related gene expression changes." (PMID 35250833, 2022). "Mutations in the PCDH19 gene have been shown to cause early-onset epilepsy, and many individuals with these mutations also display autistic features." (PMID 34523068, 2022). "PCDH19 syndrome is a monogenic epilepsy related to PCDH19, which encodes for a protein important for brain development." (PMID 35822151, 2022). "This patient presents two novel variants of the PCDH19 gene associated with a mild form of epilepsy with normal cognitive development with an apparently better prognosis." (PMID 35978409, 2022). "Here, we report a case of a 4-years old female with PCDH19-related epilepsy caused by new variants in the PCDH19 gene." (PMID 35978409, 2022). "An X‐linked female limited inheritance pattern is quite exceptional and only known from craniofrontonasal syndrome caused by EFNB1 mutations (MIM# 304110) and epilepsy in females caused by PCDH19 mutations variants (MIM# 300088)." (PMID 35001458, 2022).
epilepsy (continued). "Mutations in the protocadherin 19 gene (PCDH19) are associated with a female-restricted form of epilepsy." (PMID 35860011, 2022). "PCDH19-related epilepsy is a rare X-linked type of epilepsy caused by genomic variants of the Protocadherin 19 (PCDH19) gene." (PMID 35978409, 2022). "Autism, intellectual disabilities, and epilepsy are related to defects in the expression or function of protocadherins, and mutations in PCDH19 gene cause early infantile epileptic encephalopathy-9 (EIEE9) in humans." (PMID 35252421, 2022). "As epilepsy can also be caused by impaired interneuron migration, we studied the role of PCDH19 in cortical interneurons during embryogenesis." (PMID 36389226, 2022). "The targeted resequencing analysis of a panel of 40 genes responsible for epilepsy with febrile seizures identified the two variants c.1006G > A (p.Val336Met) and c.1014C > A (p.Asp338Glu) in the gene PCDH19 (canonical transcript NM_001184880.2)." (PMID 35978409, 2022). "Protocadherin 19 (PCDH19) syndrome is a type of epilepsy related to the PCDH19 gene (X-linked), which encodes for a protein that seems to regulate gamma-aminobutyric acid type A receptors (GABAAR)." (PMID 36004035, 2022). "To date, close to 200 PCDH19 pathogenic variants have been reported, which makes this gene one of the most commonly mutated in epilepsy." (PMID 35408865, 2022). "PCDH19 syndrome is a monogenic epilepsy related to the protein protocadherin-19 (PCDH19) gene, which encodes for a protein important for brain development." (PMID 35822151, 2022). "Protocadherin 19 clustering epilepsy is caused by X-linked protocadherin 19 protein loss of function." (PMID 35528232, 2022). "The BBB alteration during inflammation is predisposed to the recurrence of seizures of PCDH19-related epilepsy." (PMID 35822151, 2022). "A case report consisted of five females with PCDD19 mutation-related epilepsy who developed cortical malformations, including focal cortical dysplasia and PCDH19, which is thought to play a role in neuronal migration." (PMID 34833120, 2021). "Mutations in SCN1A and PCDH19 are well known to cause several types of epilepsy that are associated with FS." (PMID 33407677, 2021). "PCDH19 variants cause early-onset developmental epileptic encephalopathy clustering epilepsy (CE), with altered steroidogenesis and NHR-related gene expression being identified in these individuals." (PMID 34575929, 2021). "Certainly, mosaicism itself is pathogenic in certain epilepsies, such as X-linked mutations in PCDH19." (PMID 34235638, 2021). "In this study, we aimed to investigate variations in distributional characteristics and the clinical implications of variant type in PCDH19-related epilepsy." (PMID 33262389, 2021). "One of the most commonly implicated genes in epilepsy is the protocadherin 19 (PCDH19) gene located on chromosome Xq22.1." (PMID 35111125, 2021). "This review aims to analyze the highly variable phenotypic expression of PCDH19 gene mutation associated with epilepsy." (PMID 35111125, 2021). "This review aims to analyze the phenotypic expression of PCDH19 gene mutation associated with epilepsy." (PMID 35111125, 2021). "More than one hundred different PCDH19 pathogenic variants, located in the extracellular domain of the protein, have been associated with epilepsy, mostly in females, and recently were also detected in males." (PMID 33557955, 2021). "With more than 175 mutations reported to date, PCDH19 is now clinically considered as the second major disease gene implicated in epilepsy, after SCN1A." (PMID 34201522, 2021). "The most frequent clinical expression of PCDH19 mutation is epilepsy and mental retardation limited to female (EFMR) characterized by epileptic and non-epileptic symptoms affecting mainly females." (PMID 35111125, 2021).
epilepsy (continued). "Mutations or partial deletion of PCDH19 lead to an X-linked form of childhood clustering epilepsy, which is usually resistant to antiepileptic drugs, with early onset seizures, initially associated with fever." (PMID 34201522, 2021). "High-throughput sequencing analysis showed that PCDH19 (protocadherin 19), a gene associated with epilepsy, was regulated by Bmal1." (PMID 34261484, 2021). "Mosaicism is increasingly appreciated as a factor in the occurrence and variability of genetic disease, with mosaic pathogenic variants found in up to 8% of affected probands with other X-linked neurodevelopmental disorders such as CDKL5 and PCDH19 epilepsy." (PMID 34828275, 2021). "Although PCDH19 mutations cause epilepsy, the expression of PCDH19 in individuals with acquired epilepsy has not been reported." (PMID 34261484, 2021). "PCDH19 is a protocadherin, which has been linked to epilepsy, autism and behavioral problems, aggression, and photosensitivity." (PMID 31455857, 2020). "Pathogenic variants in the protocadherin 19 gene (PCDH19), located at Xq22, were originally reported in females with epilepsy and intellectual disability and, in a small percentage, Dravet-like syndrome phenotype." (PMID 33551717, 2020). "Protocadherin-19 (PCDH19) pathogenic variants cause an early-onset seizure disorder called girls clustering epilepsy (GCE)." (PMID 32366910, 2020). "Mutations in PCDH19 on the X chromosome cause epilepsy and intellectual disability preferentially in females, which is also known as Dravet-like syndrome." (PMID 32722525, 2020). "The X-chromosome gene PCDH19 encodes the cell-adhesion protein protocadherin-19 and is responsible for a female-limited epilepsy with intellectual disability and autistic features." (PMID 32899411, 2020). "Protocadherin-19 (PCDH19) pathogenic variants cause an infantile onset seizure disorder called girls clustering epilepsy (GCE)." (PMID 32366910, 2020). "Mutations in PCDH19 are associated with epilepsy, intellectual disability and behavioral disturbances, mostly related to females." (PMID 32425876, 2020). "Mutations in protocadherin 19 (PCDH19) chromosome X-linked gene, leads to Epilepsy in Females with Mental Retardation (EFMR) disease, cognitive impairments, and autistic phenotype." (PMID 33519379, 2020). "In mice and humans, epilepsy occurs only in heterozygous females who have a mixture of PCDH19 wild-type (WT) and mutant cells caused by random X-inactivation; it does not occur in hemizygous PCDH19 mutant males." (PMID 31747920, 2019). "Structural studies, validated with analyses of epilepsy-causing mutations, indicate that PCDH19 uses an extensive but weak antiparallel EC1–4 adhesive interface ideally suited to encode specificity." (PMID 31583286, 2019). "And, our report found four novel mutations which expand the spectrum of PCDH19 mutations associated with epilepsy in females." (PMID 31714027, 2019). "Pathogenic variants in PCDH19 cause a type of early infantile epileptic encephalopathy that is sometimes referred to as epilepsy and mental retardation limited to females." (PMID 28837158, 2018). "Given the central role of GABAAR in epilepsy and comorbidities of neurodevelopmental disorders, we decided to investigate the PCDH19-GABAAR association in more detail." (PMID 29360992, 2018). "Exome sequencing of a multigene epilepsy panel revealed three mutations in the PCDH19 gene in a mosaic male and two unrelated females." (PMID 29866057, 2018). "Since the discovery of its involvement in PCDH19-FE in 2008, PCDH19 has rapidly become the second most clinically relevant gene in epilepsy after the Dravet syndrome causative gene SCN1A." (PMID 29360992, 2018). "Since the initial description of the PCDH19 gene, the evidence of a link between the clinical features of epilepsy and de novo or familial mutations in the PCDH19 gene has increased." (PMID 29866057, 2018).
epilepsy (continued). "Aberrant patterns of brain development that impair neuronal migration and circuitry formation are often associated with epilepsy and recently cortical malformations have been identified in PCDH19-FE patients." (PMID 29360992, 2018). "PCDH19 encodes a delta-protocadherin, and mutations of PCDH19 are associated with epilepsy and mental retardation." (PMID 28785060, 2017). "Pathogenic variants in the PCDH19 gene are associated with epilepsy, intellectual disability (ID) and behavioural disturbances." (PMID 28669061, 2017). "Mutations in the X-linked gene Protocadherin-19 (Pcdh19) cause female-limited epilepsy and mental retardation in humans." (PMID 28724954, 2017). "To date, well over 100 distinct mutations in PCDH19 have been identified in epilepsy patients, making it the second most clinically relevant gene in epilepsy." (PMID 27787195, 2016). "Such mosaicism may also cause cellular interference, a mechanism also proposed for PCDH19 clustering epilepsy, another disorder with drug-resistant seizures and seizure clustering." (PMID 41153413, 2025). "Emerging genetic research has identified mutations in genes such as SCN1A and PCDH19, which are associated with specific forms of epilepsy and may offer early diagnostic markers for high-risk children." (PMID 40809839, 2025). "Although a thorough clinical examination of the patients was performed prior to genetic testing, in the asymptomatic mothers carrying the pathogenic PCDH19 mutation, the possibility of an unrecognized and, thus, undocumented mild epilepsy in the mother’s childhood cannot be excluded." (PMID 38891919, 2024). "Although Patient 3 is considered atypical among patients with PCDH19-associated epilepsy, the detected PCDH19 mutation may explain some of her symptoms, such as cognitive regression, as a consequence of epileptic encephalopathy." (PMID 38891919, 2024). "Furthermore, PCDH19, known to cause epilepsy with mental retardation, was reported in two unrelated patients with developmental delay and intellectual disability." (PMID 37628333, 2023). "The interaction between the cytoplasmic domains of PCDH19 with the alpha subunits of the GABAa receptor could alter the excitatory-inhibitory balance underlying epilepsy." (PMID 35111125, 2021). "Our findings could contribute to diagnosis of PCDH19-related epilepsy and could help to elucidate the pathogenic mechanisms of this disease." (PMID 33262389, 2021). "Missense and truncating variants in protocadherin 19 (PCDH19) cause PCDH19-related epilepsy." (PMID 33262389, 2021). "It is not well known how mutations of PCDH19 lead to the development of epilepsy." (PMID 35111125, 2021). "PCDH19-related epilepsy is caused by pathogenic variants in the PCDH19 gene." (PMID 33262389, 2021). "To date, more than 200 variants have been reported in patients with PCDH19-related epilepsy." (PMID 33262389, 2021). "PCDH19-related epilepsies illustrate an unusual X-linked inheritance pattern." (PMID 34966409, 2021). "The hallmark feature of PCDH19-associated epilepsy is that seizures occur in clusters." (PMID 29892053, 2019). "In this study, we have screened 152 children with fever‐sensitive epilepsy and found PCDH19 mutation in 10 female probands who also had cluster seizures with or without cognitive impairment or mental retardation in order to further understand the clinical and mutational features of PCDH19‐GCE." (PMID 31714027, 2019). "PCDH19 mutations‐related epilepsy has incomplete penetration rate and phenotypic heterogeneity." (PMID 31714027, 2019). "And, our report expands the spectrum of PCDH19 mutations associated with epilepsy in females." (PMID 31714027, 2019). "Notably, human PCDH19 mutations have been linked to early onset epilepsy and intellectual disability in females." (PMID 31477701, 2019).